TOP2A (DNA topoisomerase II alpha)
Diseases named in the same sentence as TOP2A in open-access papers (continued):
Sharing a sentence is not in itself a finding about the gene and the disease.
cancer (continued). "In humans, Top2 is expressed as the isoenzymes Top2α and Top2β, with the former expressed in proliferative cells (including cancer cells) and the latter in quiescent cells." (PMID 35326728, 2022). "They observed that DNA topoisomerase II alpha (TOP2A) expression was elevated in brain metastases from all three cancers." (PMID 36612206, 2022). "Overexpression of TOP2A was existed in almost all cancer types, and related to poor prognosis and advanced pathological stages in most cases." (PMID 35778520, 2022). "In conclusion, our pan-cancer analysis of TOP2A showed that TOP2A was highly expressed in most cancers, and significantly correlated with cancer development and patient survival prognosis." (PMID 35873470, 2022). "The differential expression of TOP2A in cancer tissues and normal tissues was obtained from the TIMER database." (PMID 35033076, 2022). "Though the pan-cancer analysis of TOP2A in our research has a certain significance, there are still some limitations in our research such as data resources and experimental proof." (PMID 35873470, 2022). "For the first time, we analyzed potential oncogenic roles of TOP2A in 33 cancer types via The Cancer Genome Atlas (TCGA) database." (PMID 35778520, 2022). "We first analyzed TOP2A expression in cancer types with enough adjacent normal tissues in TCGA project." (PMID 35778520, 2022). "Clusters 6 and 7 (lymphH6 and lymphH7) exhibited higher levels of pro-survival/cell cycle regulation genes (BIRC5, TOP2A, CENPF) associated with metabolically active cancer pathways." (PMID 34579762, 2021). "Cluster 3 was highlighted by the significantly increased transcripts of proliferating marker genes, including MKI67, PCNA and DNA Topoisomerase gene, TOP2A, suggesting activated cell proliferation in this cancer cell cluster." (PMID 34055623, 2021). "The agent, which inhibits TOP2A, is used to treat some types of cancers such as lung, blood, and breast cancers." (PMID 34782700, 2021). "Cluster 0 and 6 were enriched in cells expressing genes related to cell cycle and cancer-associated proliferation (SFRP2, CENPF, TOP2A, UBE2C, CRABP2, MYC)." (PMID 33771987, 2021). "Top2α is mostly expressed in cells with high proliferation rates such as cancer cells, whereas Top2β is expressed on quiescent cells such as myocardium." (PMID 34582653, 2021). "Recent studies have revealed that TOP2A plays a vital role in the genesis of many malignant tumours." (PMID 33527765, 2021). "For instance, doxorubicin inhibits both Top2a and Top2b, inhibiting Top2a have an anti-cancer effect while inhibiting Top2b have a cardiac side effect." (PMID 34026868, 2021). "Using the Oncomine database, TOP2A was observed to be upregulated in cancers relative to healthy hepatic tissues." (PMID 34939898, 2021). "The expression of TOP2A is commonly altered at both the gene copy number and gene expression levels in cancer cells." (PMID 34093807, 2021). "Whereas the median expression of TOP2A was 31.3% higher than the median in all other cancer cell lines in DepMap RNA-seq data (P = 2 × 10−3), the median expression of TOP2B was 87.1% higher (P = 1.3 × 10−7)." (PMID 34753908, 2021). "It will be of interest to broaden our study to other types of cancers, where TOP2A targeting agents are frequently used." (PMID 34162828, 2021). "TOP2A is deemed as an essential gene for cancer cell division, since its expression is specific for the S and M phases of cell cycling, and is required for DNA replication and disentangling interlinked chromosomes for mitosis." (PMID 34359577, 2021). "Firstly, RT-qPCR assays using a cohort of 40 specimens indicated that about 80% of the TOP2A mRNA levels within HCC tissues increased as compared with non-carcinoma samples." (PMID 34939898, 2021). "In particular, the Top2α isoform is a major target for antineoplastic agents that are widely used in cancer chemotherapy." (PMID 35582608, 2020).
cancer (continued). "The study reported that TOP2A was overexpressed in HGS cell lines, associated with poor cancer-specific, progression-free survival." (PMID 32368301, 2020). "In this review, we highlight the different modifications affecting the human Top2α in healthy and cancer cells, taking advantage of the structure-function information accumulated in the past decades." (PMID 35582608, 2020). "We also examined the association between two other proliferation markers (TOP2A and RACGAP147) and DEPTH scores in cancer." (PMID 32917965, 2020). "We also overview the relationships among the regulation of Top2α by PTM, the level of PTM in cancer cells, and the resistance to anti-Top2 therapeutic compounds." (PMID 35582608, 2020). "In this review, we analyze the different types of modifications affecting the human Top2α in normal and cancer cells with a structure-function perspective." (PMID 35582608, 2020). "TOP2A was significantly up-regulated in the cancer samples and down-regulated in the normal samples." (PMID 32368301, 2020). "Cancer cells and highly proliferative T cells rely on Top2α more than other cells, because they divide more rapidly." (PMID 32193368, 2020). "To gain insights into how TOP2A induced proliferation and invasion in cancer cells, we then explored which signaling pathways were involved in this process." (PMID 32201520, 2020). "Non-heterocycle naphthoquinone-TSC CuC 21 and bis-TSC CuC 22 are Top2α inhibitors acting as poisons; they induce apoptosis in various human cancer cell lines and delay colorectal growth of carcinoma xenografts in mice." (PMID 33027952, 2020). "Because of their relevance in cancer therapy, Top2α PTM have been characterized mostly in cancer cell lines, while the extent of PTM in the homeostasis of normal cells has been somewhat neglected." (PMID 35582608, 2020). "Top2α is a prominent target for anti-cancer drugs and is highly regulated by post-translational modifications (PTM)." (PMID 35582608, 2020). "As indicated in previous studies, our results confirmed that the overexpression of TOP2A in cancer is related to worse prognosis 13, 14, 27-29." (PMID 32201520, 2020). "Other bioinformatic analyses showed that TOP2A was related to development in cancers of the liver, esophagus, stomach, cervix, and lung, among others." (PMID 33505422, 2020). "Several studies demonstrated that TOP2A participated actively in carcinogenesis in a range of cancer types, including breast, endometrial, and colon; higher TOP2A expression was indicative of poor prognosis 8-10." (PMID 32368301, 2020). "The results showed that TOP2A expression was significantly higher in cancer tissues comparing to matched normal sections." (PMID 31528121, 2019). "Then, to validate the aberrant gain of expression of TOP2A in NSCLC, GEPIA was firstly performed, and the results showed that TOP2A was up-regulated in cancers comparing to normal tissues." (PMID 31528121, 2019). "Numerous studies have shown that PRC1 and TOP2A play roles in multiple cancers and extensive studies have shown that PRC1 is involved in cell cycle processes." (PMID 31737106, 2019). "And both GEPIA analysis and immunohistochemistry experiment (IHC) confirmed that TOP2A was aberrant gain of expression in cancer comparing to normal tissues." (PMID 31528121, 2019). "RNA expression of TOP2A, PCNA, SOX2, EZH2, ZEB1 genes associated with cell cycle, cancer cell ‘stemness’, and FOXM1‐FOXO activities was similarly affected in both cases." (PMID 30927552, 2019). "Among the listed drugs, paclitaxel was considered as a potential drug for cancer therapy based on its interaction with TOP2A." (PMID 31139019, 2019). "A Cancer specific survival, progression free survival and recurrence free survival curve between TOP2A high and low expression patients with muscle invasive bladder cancer (MIBC, n=130)." (PMID 31216997, 2019).
cancer (continued). "Given the essential role of TOP2A in malignant tumors, TOP2A has held the interest of researchers developing targeted anticancer drugs." (PMID 31216997, 2019). "Several studies have reported that higher expression levels of TOP2A are indicative of poor prognosis in a variety of human cancers." (PMID 31216997, 2019). "IHC experiment validated the aberrant gain of expression of TOP2A in cancer comparing to normal tissues." (PMID 31528121, 2019). "Doxorubicin and etoposide are two most clinically active anticancer agents targeting TOP2A in different cancers." (PMID 31216997, 2019). "This complex can influence susceptibility to TOP2 inhibitor therapy as units like SMARCB1 are involved in loading TOP2A onto DNA, and thus can determine how many DNA breaks a cancer cell will have when exposed to a TOP2 poison." (PMID 29988316, 2018). "High expression of TOP2A is detected in several types of cancer, and more importantly TOP2A has been acknowledged as a cancer target in clinical application." (PMID 30369945, 2018). "DOX chemotherapy displays a high efficacy, because of the extremely raised expression of Top2α in cancer cells." (PMID 30483123, 2018). "TOP2A is commonly altered at both the gene copy number and gene expression level in cancer cells and has been suggested to play an important role in chromosome instability in human cancers." (PMID 29769567, 2018). "The top five upregulated DEGs, including CDK1, CCNB1, TOP2A, MYC, and PCNA, were associated with cell mitosis and involved in the development of cancer." (PMID 30092828, 2018). "In HR+/HER2− cancers, LN+ status and expression of MMP11 and TOP2A were independently associated with the increased risk of recurrence." (PMID 28409241, 2017). "The high expression of TOP2A in tumor tissue predicted poor prognosis in some tumor patients and also promoted lymph node metastasis and distant metastasis in malignant tumors." (PMID 28355294, 2017). "It would be interesting to explore the anti-cancer effect of the 10 herbs through DNA topoisomerase II-alpha-dependent cellular cytotoxicity." (PMID 28212580, 2017). "TOP2A is a widely used target of existing anti-cancer drugs and it's expression is often used as a cancer cell marker because of it's role in cell proliferation." (PMID 28410543, 2017). "The cellular abundance of TOP2A is reported to determine the efficacy of anthracycline based chemotherapy in various cancers." (PMID 28813519, 2017). "Doxorubicin induces cancer cell death by many mechanisms, the most notable is Top2A poisoning, and also the down-regulation of Top2A is obviously detected in doxorubicin resistant MCF7 cells." (PMID 26824188, 2016). "The anticancer effects of doxorubicin are believed to occur through the inhibition of topoisomerase-II enzymes (Top2β and Top2α) and the subsequent blockage of DNA resealing during replication that eventually leads to cell death of cancer cells." (PMID 27142468, 2016). "High level of TOP2A as an indicator of more aggressive behavior and advanced stage was reported for several cancers." (PMID 26560244, 2015). "Certain oncogenes, including human epithelial growth factor receptor-2 (HER2) and topoisomerase II alpha (TOP2A), have been investigated in various cancer subtypes as targets for cancer therapy, as well as biomarkers for prediction of response." (PMID 25695068, 2015). "Both Ki-67 and TOP2A expression can be used as molecular biomarkers of cell proliferation in various cancers." (PMID 25695068, 2015). "Given that they are highly expressed in aggressive cancer cells and are essential to cancer cell survival, top1 and top2α are potential drug targets for treating human malignancies." (PMID 26462155, 2015).
cancer (continued). "Although TOP2A is highly expressed in cancer cells in vivo, attempts to ectopically express this protein in vitro have been unsuccessful because of concomitant induction of apoptosis." (PMID 26560244, 2015). "We applied ultracentrifugation in glycerol gradients to investigate the stability of Top2α-DNA complexes after the treatment of NaClO4, and the effect of an anti-cancer drug." (PMID 24809695, 2014). "To test that our anisotropy assays can be effective in identifying other known Top2α-targeting anti-cancer drugs besides teniposide (VM26), we measured anisotropy after NaClO4 treatment with etoposide (VP16), mAMSA, and mitoxantrone." (PMID 24809695, 2014). "The depletion of TOP2B and TOP2A suggests an explanation for the reported DRZ interference with cancer response to anthracyclines and for DRZ side-effects." (PMID 25406834, 2014). "Increasing evidence has demonstrated that the expression levels of ERCC1, TYMS, TUBB3, RRM1 and TOP2A are closely correlated with the pathogenesis of carcinomas." (PMID 24926347, 2014). "For this reason, TOP2A is the target of the most widely successful drugs in cancer chemotherapy, such as TOP2A poisons, which stabilize TOP2A-DNA cleavage complexes and create DSBs, leading to chromosome damage and cell death." (PMID 23928695, 2013). "Our findings suggest that the dual activity of bDMC on TOP2A represents a novel therapeutic strategy to induce persistent apoptosis in cancer cells and identify NF-Y regulation as a promising approach in anti-cancer therapy." (PMID 23928695, 2013). "The presence of TOP2A amplification tends to a slightly worse overall survival (p = 0.08 and p = 0.06) compared to adult cancers." (PMID 24216996, 2013). "Discovered as a Topoisomerase 2A (TOP2A) poison, etoposide is now a frontline chemotherapeutics in treating various human cancers." (PMID 24103454, 2013). "We highlight that bDMC triggers DNA damage in cancer cells by targeting TOP2A, both through inhibition of its enzymatic activity and through repression of its NF-Y-dependent transcription." (PMID 23928695, 2013). "To understand the long term influence of TOP2A expression on patient outcome, we need to consider newer functional aspects of TopoIIa protein and how these affect the fate of cancer cells when attacked by cytotoxic agents, such as anthracyclines." (PMID 22240029, 2012). "This study showed a total of five genes amoung which two genes CDK1 and TOP2A differentially expressed across five cancer types." (PMID 22952714, 2012). "Both CDK1 and TOP2A genes have been considered as multi-type cancer markers by a previous meta-analysis of cancer microarray data." (PMID 22952714, 2012). "Pharmacological targeting of TOP2A, which is extensively applied in cancer treatment, exploits this mechanism." (PMID 22111588, 2011). "Western blotting demonstrated abundant TOP2A enzyme expressions in N1-S1 cells using protein extracts from cancer cells and normal Clone 9 hepatocytes." (PMID 20649994, 2010). "TOP2A was underexpressed in Ca Ski compared to other cancer cell lines." (PMID 40507244, 2025). "TOP2A has been reported to be a prognostic marker for various cancers." (PMID 40831931, 2025). "The involvement of TOP2A in cancer is not limited to its role as a biomarker." (PMID 40831931, 2025). "Accumulating evidence has highlighted the pivotal role of TOP2A in cancer progression." (PMID 41235254, 2025). "Further studies could investigate the precise role of TOP2A in these cancers, particularly focusing on its interaction with other molecular pathways." (PMID 40869426, 2025). "Furthermore, inhibition of TOP2A activity has been mostly studied in cancer cells, due to its importance and use in cancer treatment." (PMID 39885205, 2025). "In addition, miR-144-3p has been shown to suppress cell proliferation and invasion in HCMV-positive GB by targeting TOP2A, a well-known biomarker in cancer progression and therapy." (PMID 41004517, 2025).
cancer (continued). "Additionally, previous studies have identified a dual upregulation of EZH2 and TOP2A during cancer progression." (PMID 40271060, 2025). "The possibility of TOP2A inhibition has raised persistent concerns that dexrazoxane may reduce the anticancer effectiveness of anthracyclines in cancer patients." (PMID 40425539, 2025). "Indeed, TOP2A, highly expressed in various malignancies, has a critical role in the initiation and progression of cancer." (PMID 40271060, 2025). "Studies have shown that when DNA damage occurs in cancer cells, nuclear transglutaminase 2 can rapidly accumulate at DNA double-strand break sites, and directly interact with TOP2A to promote DNA double-strand break repair, which will lead to drug resistance in cancer cells." (PMID 41301416, 2025). "In addition, several TOP2A inhibitors, such as etoposide and doxorubicin, have shown promising results in preclinical studies for cancer treatment." (PMID 38600056, 2024). "Also, TOP2A was overexpressed in various cancer malignancies including breast, ovarian, pancreatic and prostate, and it associated to poor prognosis and advanced pathological stages in most cancer types." (PMID 38957610, 2024). "Significant overexpression of the TOP2A gene has been noted across a range of human cancers." (PMID 38730293, 2024). "Thus, we analyzed the effects of TOP2A inhibition by etoposide on cancer stem cell self-renewal marker Oct-4 and Sox2." (PMID 38957610, 2024). "Therefore, there is interest in designing specific inhibitors of Top2A, since this isoform is very active in dividing cells (like cancer cells) and is reduced in expression in many differentiated tissues." (PMID 38891861, 2024). "CCNA2, TTK, TOP2A, AURKA, AURKB and BUB1B are also closely associated with cancer." (PMID 39537209, 2024). "However, the inhibition of TOP2A dramatically decrease the cellular proliferation of various cancer cells." (PMID 38957610, 2024). "The generation of 2–4 nucleotide insertions is not the only mutational event seen in human cancers expressing Top2α-K743N." (PMID 39408578, 2024). "For example, never-smokers displayed a greater proportion of hypomethylated differentially methylated regions (hypoDMRs) and a greater number of recurrently hypomethylated promoters, including those of ASPSCR1, TOP2A, DPP9, and USP39, all previously linked to cancer." (PMID 37742993, 2023). "TOP2A is a key enzyme in DNA replication and is a therapeutic target for breast and other cancers." (PMID 37880313, 2023). "Additionally, TOP2A expression levels were higher in tumor tissues than in the normal tissues at each cancer stage (P < 0.01)." (PMID 37985446, 2023). "It suggests that PLAU and TOP2A may be dangerous biomarkers and potential therapeutic targets for PCa and other cancers." (PMID 36741321, 2023). "Previous studies have identified EZH2 and TOP2A as comarkers of cancer progression." (PMID 38008711, 2023). "Next, we further investigated the prognostic value of TOP2A in pan-cancer using the TCGA database." (PMID 37980167, 2023). "The process of bone metastasis includes cancer cell growth, migration, invasion, homing to and residing in bone microenvironment, and osteoclastogenesis, therefore, TOP2A may be used as a new potential target for bone metastasis of LIHC." (PMID 37980167, 2023). "Furthermore, in different cancer types, the downregulation of TOP2A was found to be related to the inhibition of cell proliferation, which is in agreement with our findings of cell proliferation in the 3D BM niche-like AML model (CFSE data)." (PMID 37932837, 2023). "In vitro studies on various types of cancer have reported that sensitivity to TOP2A inhibitors depends on changes in the expression level of this gene, due to the fact that cells that are expressed at low levels show less sensitivity to drugs than those that are overexpressed." (PMID 37895364, 2023). "We further analyzed the correlation between EZH2 and TOP2A expression in cancer." (PMID 38008711, 2023).